CH25H (cholesterol 25-hydroxylase)
Diseases named in the same sentence as CH25H in open-access papers (continued):
Sharing a sentence is not in itself a finding about the gene and the disease.
diabetes (5 papers, 2017 to 2025). "Diabetes‐induced podocyte loss, as ascertained by podocyte marker WT‐1, was exacerbated in diabetic Ch25h−/− mice compared to diabetic Ch25h+/+ mice." (PMID 38816950, 2024). "In summary, the present study supports the critical role of Ch25h and its product 25‐HC in protecting against diabetes‐induced kidney endothelial cell injury." (PMID 38816950, 2024). "Our in vivo studies showed that the lack of CH25H led to apoptosis of GECs and peri‐tubular endothelial cells, indicating that CH25H has a pro‐survival effect on endothelial cells in the context of diabetes." (PMID 38816950, 2024). "Here, we investigated the role of hepatic Ch25h in the transition from metabolically healthy obesity to insulin resistance and diabetes." (PMID 28299341, 2017). "Furthermore, CH25H and 25‐HC levels are notably lower in mice with type 2 diabetes mellitus (T2DM), and CH25H knockout exacerbates cardiac dysfunction in T2DM models." (PMID 41294012, 2025). "In people with diabetes, plasma levels of the preproducts of 7α,25-OHC and 7α,27-OHC; 25-hydroxycholesterol (25-OHC), 27-hydroxycholesterol (27-OHC), together with visceral adipose tissue (VAT)-expressed cholesterol 25-hydroxylase (CH25H), are increased compared to individuals without diabetes." (PMID 39545055, 2024).
osteoarthritis (5 papers, 2021 to 2026). A noninflammatory degenerative joint disease occurring chiefly in older persons, characterized by degeneration of the articular cartilage, hypertrophy of bone at the margins and changes in the synovial membrane. "Presumably, hydroxylated cholesterol derivatives, in particular, are involved in the pathogenesis of OA, since adenoviral overexpression of CH25H or CYP7B1 in mouse chondrocytes has previously been found to cause experimental osteoarthritis." (PMID 41296055, 2025). "Adenoviral overexpression of Ch25h or Cyp7b1 in mouse joint tissues caused experimental osteoarthritis, whereas knockout or knockdown of these hydroxylases abrogated the pathogenesis of osteoarthritis." (PMID 38104944, 2024). "Recent research suggests that cholesterol 25-hydroxylase may inhibit the inflammatory response of chondrocytes by binding to the upstream target miR-10a-3p, thus potentially reducing the incidence of osteoarthritis." (PMID 39045319, 2024). "Retinoic acid-related orphan receptor α (RORα) was found to mediate the induction of osteoarthritis by alterations in cholesterol metabolism, which acts as downstream receptor of cholesterol hydroxylases, including cholesterol 25-hydroxylase (CH25H) and 25-hydroxycholesterol 7α-hydroxylase (CYP7B1)." (PMID 34149433, 2021).
breast carcinoma (4 papers, 2022 to 2025). "Six of the genes (CASP1, CCL2, ADGRE5, IL3RA, RSPO1, and STAB1) are co‐expressed with the CH25H gene in both cancers, while two genes (ANPEP in breast cancer and CCL8 in prostate cancer) are exclusively co‐expressed with the CH25H gene in one of the tumors." (PMID 41159143, 2025).
experimental autoimmune encephalomyelitis (4 papers, 2017 to 2023). An autoimmune demyelinating disease of the central nervous system that is produced experimentally in animals by the injection of homogenized brain or spinal cord in Freund's adjuvant. "Experimental autoimmune encephalomyelitis was induced in Ch25hBBBKO and control mice and we observed that the sole deletion of Ch25h in CNS ECs was sufficient to reproduce the EAE phenotype observed in the Ch25hECKO and Ch25hBECKO mice." (PMID 36715148, 2023). "Partial loss of Ch25h in ECs promotes polymorphonuclear myeloid‐derived suppressor cells (PMN‐MDSC) expansion and reduces experimental autoimmune encephalomyelitis (EAE) severity." (PMID 36715148, 2023). "A lack of Ch25h markedly increases the aggressiveness markedly of experimental autoimmune encephalomyelitis (EAE) in Ch25h−/−/ApoE−/− mice, which is a mouse model of multifaceted inflammatory disease." (PMID 32859970, 2020). "In keeping with these actions of 25-HC, Ch25h knockout mice show exacerbated experimental autoimmune encephalomyelitis (EAE), an IL-17-driven inflammatory disease model of MS, and increased susceptibility to septic shock." (PMID 27878760, 2017). "Using floxed‐reporter Ch25h knock‐in mice, we trace Ch25h expression to CNS endothelial cells (ECs) and myeloid cells and demonstrate that Ch25h ablation specifically from ECs attenuates experimental autoimmune encephalomyelitis (EAE)." (PMID 36715148, 2023).
ZIKV infection (4 papers, 2018 to 2025). "Our prior studies showed CH25H upregulation in microglia following ZIKV infection." (PMID 40688087, 2025). "Previously, we reported that cholesterol-25-hydroxylase (CH25H) and its metabolite 25-hydroxycholesterol (25-HC) had a broad antiviral activity in inhibiting Zika, Ebola, and HIV-1 infection." (PMID 30524435, 2018).
chronic obstructive pulmonary disease (3 papers, 2012 to 2024). A chronic and progressive lung disorder characterized by the loss of elasticity of the bronchial tree and the air sacs, destruction of the air sacs wall, thickening of the bronchial wall, and mucous accumulation in the bronchial tree. "In disease models, such as chronic obstructive pulmonary disease (COPD), Ch25h expression was increased in AM and alveolar cells, with higher levels of Ch25h corresponding to increased IL-8 and neutrophil recruitment in lung tissue." (PMID 36831236, 2023). "Furthermore, CH25H expression was significantly increased in lung tissue of chronic obstructive pulmonary disease (COPD) patients." (PMID 38716981, 2024). "Recently, we demonstrated that the expression of cholesterol 25-hydroxylase in alveolar macrophages and pneumocytes in human lung tissues and the level of 25-HC in sputum from patients with chronic obstructive pulmonary disease (COPD) are increased compared to non-smoker control subjects." (PMID 22849850, 2012).
Hepatic steatosis (3 papers, 2019 to 2025). Steatosis is a term used to denote lipid accumulation within hepatocytes. "Increased levels of cholesterol 25-hydroxylase (Ch25 h) and its enzymatic by-product 25HC in the liver prevent high-fat diet-induced hepatic steatosis." (PMID 36909161, 2023).
lung carcinoma (3 papers, 2022 to 2024). "Loss of CH25H in antigen presenting cells isolated from human lung tumors is associated with tumor growth and lung cancer progression." (PMID 36333297, 2022). "Partial loss of CH25H expression occurs in human intratumoral APC and is associated with lung cancer growth and progression." (PMID 36333297, 2022). "Online public databases were used to analyze the expression level, prognostic value, gene-pathway enrichment, and immune infiltration of CH25H in lung cancer patients." (PMID 36564433, 2022). "Thus, to address this problem, this study aimed to explore the role and contribution of Cholesterol 25-Hydroxylase (CH25H) as a potential diagnostic and prognostic marker in lung cancer." (PMID 36564433, 2022). "In our own studies, we next focused on CH25H expression and its importance in DCs in lung cancer." (PMID 36333297, 2022). "Our findings promote an improved understanding of the mechanisms of CH25H in lung cancer and demonstrate that leukocyte CH25H expression could be used to develop a rapid, inexpensive, and powerful diagnostic strategy for predicting the risk of lung cancer metastasis." (PMID 36564433, 2022). "Consistent with the function of ATF3 in suppressing CH25H expression, ATF3-null DCs exhibited a reduced OVA proteolysis, which was not increased after treatment with the lung cancer cell-conditioned media." (PMID 36333297, 2022).
Obesity (3 papers, 2017 to 2024). Accumulation of substantial excess body fat. "This in vivo gain-of-function study indicates elevated hepatic Ch25h levels are able to improve insulin sensitivity and therefore induce a metabolically healthy form of obesity." (PMID 28299341, 2017). "Our data are also indicative of Ch25h expression where not only is it downregulated in the wake of obesity, but also its importance is mainly at the point of decision between insulin resistance and insulin sensitivity." (PMID 28299341, 2017). "It has been shown that Ch25h is involved in the regulation of lipid metabolism; therefore our first aim was to investigate the role of hepatic Ch25h levels in obesity." (PMID 28299341, 2017).
asthma (2 papers, 2024 to 2025). "In addition, cholesterol-25-hydroxylase was identified as a major lipid metabolism gene in asthma and showed high expression in two mouse models of asthma." (PMID 40559469, 2025).
Autoimmunity (2 papers, 2017). The occurrence of an immune reaction against the organism's own cells or tissues. "Moreover, in EAE, expression of EBI2 receptor in Th17 cells, CH25H in microglia and CYP7B1 in infiltrating immune cells have been found to be increased demonstrating EBI2/oxysterol role as a mediator of autoimmunity and inflammation." (PMID 29246262, 2017). "To further address the in vivo relevance of Ch25h in inducing IL-27-driven TR1 cells and the potential effect on regulating autoimmunity and tissue inflammation, we conducted repeated in vivo treatments with anti-CD3 to induce IL-10+ regulatory T cells, that have been shown to be IL-27 dependent." (PMID 28993775, 2017).
glioma (2 papers, 2019 to 2021). A benign or malignant brain and spinal cord tumor that arises from glial cells (astrocytes, oligodendrocytes, ependymal cells). "Previous findings showed that elevated CH25H expression promoted chemotactic monocyte recruitment of glioma cells." (PMID 34568059, 2021). "Additionally, analysis based on 1,018 Chinese glioma patients suggested that CELF5 (P < 0.001), GSG1L (P = 0.002), AMACR (P < 0.001), CYP27A1 (P < 0.001), CYP46A1 (P < 0.001), and CH25H (P = 0.046) were all prognostic indicators in Kaplan-Meier survival analysis." (PMID 32117422, 2019).
inflammatory bowel disease (2 papers, 2025). A spectrum of small and large bowel inflammatory diseases of unknown etiology. "For instance, lipopolysaccharide (LPS) induces the upregulation of CH25H in both mouse and human macrophages, which may be pivotal in the pathogenesis of inflammatory bowel disease (IBD), a leading cause of CRC." (PMID 41020041, 2025).
ischemic stroke (2 papers, 2023). A stroke disorder caused by obstruction of blood flow to the brain, due to thrombotic (local blood clot formation) or embolic (due to a blood clot or other material traveling from another site) event. "In this study, we identified 3 distinct ischemic stroke-associated microglia (ISAM) specifically marked with MKI67 (MG4), OASL (MG5), and CH25H (MG6), respectively." (PMID 37183260, 2023). "Infarct volume was significantly increased after ischemic stroke in Ch25h−/− mice compared with Ch25h+/−." (PMID 37905592, 2023). "We identified a relatively homeostatic subcluster with enhanced antigen processing and three “ischemic stroke associated microglia” (ISAM): MKI67+, CH25H+ and OASL+ subclusters." (PMID 37183260, 2023). "To decipher the role of Ch25h in microglia after ischemic stroke, we subjected Ch25h−/− mice to 60-min tMCAO, giving the finding that Ch25h was mainly expressed in microglia of ischemic stroke brain." (PMID 37183260, 2023). "Ch25h−/− mice developed significantly increased infarct volume following ischemic stroke compared to Ch25h+/−." (PMID 37183260, 2023). "In addition, using systemic in vivo DNA labeling with 5-ethynyl-2′-deoxyuridine (EdU), we found EdU were incorporated in OASL+ MG5 and CH25H+ MG6 subclusters in the ischemic stroke brain 3 days after stroke." (PMID 37183260, 2023). "Our data reveal previously unrecognized roles of the newly defined CH25H+ and OASL+ microglia subclusters following ischemic stroke, with novel insights for precise microglia modulation towards stroke therapy." (PMID 37183260, 2023).
leukemia (2 papers, 2015 to 2019). A malignant (clonal) hematologic disorder, involving hematopoietic stem cells and characterized by the presence of primitive or atypical myeloid or lymphoid cells in the bone marrow and the blood. "Further information should be accumulated about the data of CH25H gene in MDS/leukemia cases and the effects of DNMT inhibitors on the methylation status of CH25H as well as clinical outcome." (PMID 26577244, 2015). "We examined CH25H mRNA expression level in five MDS/leukemia cell lines (HL-60, MDS-L, MDS92T, U937 and K562) by quantitative real-time PCR (q-PCR)." (PMID 26577244, 2015). "Although CH25H mRNA expression level was originally low in MDS/leukemia cell lines, exposure to DNMT inhibitors enhanced CH25H mRNA expression." (PMID 26577244, 2015). "DAC promoted the expression of CH25H in various MDS/leukemia cell lines, particularly in MDS-L." (PMID 26577244, 2015). "DAC treatment led to enhanced CH25H mRNA expression in most of primary leukemia cells studied." (PMID 26577244, 2015). "Further investigations of the promoter analysis of CH25H gene and therapeutic effects of DNMT inhibitors on MDS/leukemia will be warranted." (PMID 26577244, 2015).
lung adenocarcinoma (2 papers, 2022 to 2023). A carcinoma that arises from the lung and is characterized by the presence of malignant glandular epithelial cells. "It was also reported that low expression of CH25H in leukocytes was significantly associated with lung adenocarcinoma metastasis." (PMID 37981011, 2023). "The expression level of CH25H was significantly reduced in lung adenocarcinoma (LUAD), which is associated with a higher disease stage, but not in lung squamous cell carcinoma (LUSC)." (PMID 36564433, 2022).
multiple sclerosis (2 papers, 2017 to 2025). A progressive autoimmune disorder affecting the central nervous system resulting in demyelination. "It has also been found that CH25H is up-regulated during demyelination as well remyelination in animal models of multiple sclerosis, EAE, to promote myelination." (PMID 29246262, 2017). "Modulation of EBI2 signalling and/or local concentrations of CH25H, CYP7B1 and HSD3B7 in the brain and the brain blood vessels might result in disease-modulatory effects with potential therapeutic applications in the treatment of neuroinflammatory diseases including multiple sclerosis." (PMID 39999050, 2025).
pneumococcal infection (2 papers, 2014 to 2023). Infections with bacteria of the species streptococcus pneumoniae. "We showed that transcription of Ch25h significantly differed between resistant BALB/c and susceptible CBA/Ca during pneumococcal infection and between control animals." (PMID 24594938, 2014).
type 2 diabetes (2 papers, 2017 to 2025). "Further studies are necessary regarding the exact mechanisms of hepatic Ch25h action in the development of insulin resistance and subsequently type 2 diabetes." (PMID 28299341, 2017).
X-linked adrenoleukodystrophy (2 papers, 2020 to 2022). X-linked adrenoleukodystrophy (X-ALD) is a peroxisomal disorder resulting in cerebral demyelination, axonal dysfunction in the spinal cord leading to spastic paraplegia, adrenal insufficiency and in some cases testicular insufficiency. "25-Hydrocholesterol (25-HC) is a downstream product of cholesterol 25-hydroxylase, and this enzyme is increased in X-linked adrenoleukodystrophy (X-ALD) patient-derived induced pluripotent stem cells." (PMID 35783102, 2022).
adenovirus infection (1 paper, 2023). "The expression levels of MMP1, IL6, IL8, and PTGS2 increased upon CH25H overexpression via adenovirus infection in human GFs." (PMID 38036731, 2023).
amyloidosis (1 paper, 2025). A disorder characterized by the localized or diffuse accumulation of amyloid protein in various anatomic sites. "In the SMC-calc vs. SMC comparison based on limma, clusters related to high-density lipoprotein (HDL) assembly (PF4V1, APOA1, LPXN, AFP, A2M, and MMP1) and amyloidosis (CX3CL1, APOE, PLIN3, TGFBI, and CH25H) were identified." (PMID 41301179, 2025).
Arthritis (1 paper, 2020). Inflammation of a joint. "Synovial tissue biopsies from patients that are at risk of developing rheumatoid arthritis were obtained and high risk individuals who progressed to inflammatory arthritis displayed increased levels of 25HC-synthesising enzyme Ch25h, while those with low levels of Ch25h remained arthritis free." (PMID 32998240, 2020).
brain haemorrhages (1 paper, 2025). "To further validate our findings in this zebrafish model, we evaluated CH25H expression in post-mortem human foetal brain samples with SARS-CoV-2-associated brain haemorrhages." (PMID 40406995, 2025).
breast tumors (1 paper, 2025). "A total of 12 genes were selected for analysis based on their coexpression or lack thereof with the CH25H gene in human prostate and breast tumors." (PMID 41159143, 2025). "Analysis of the co‐expression of the overexpressed genes in human prostate and breast tumors revealed that the CH25H gene shows a significant positive correlation of expression with 37 and 36 of these genes in prostate and breast tumors, respectively." (PMID 41159143, 2025). "In human prostate and breast tumors, the CH25H gene shows a very high correlation of coexpression with the CCL2 and CCL8 genes, as is the case in the dormant‐met group." (PMID 41159143, 2025).
chronic lung disease (1 paper, 2024). According to the definitions of the American and British Thoracic Societies, including pulmonary functional tests, X-rays, and CT scans for items such as fibrosis, bronchiectasis, bullae, emphysema, nodular or lymphomatous abnormalities. "Previous reports have shown that Ch25h-dependent secretion of 25-HC occurs in macrophages in response to activation or during chronic lung diseases." (PMID 39717487, 2024).
contact dermatitis (1 paper, 2023). An inflammatory skin condition caused by direct contact between the skin and either an irritating substance or an allergen. "The CH25H gene has been characterized as exerting complex yet critical effects on immune cells; its significance has been demonstrated in skin inflammation and irritant contact dermatitis." (PMID 37646031, 2023).
Crohn disease (1 paper, 2020). A gastrointestinal disorder characterized by chronic inflammation involving all layers of the intestinal wall, noncaseating granulomas affecting the intestinal wall and regional lymph nodes, and transmural fibrosis. "A strong correlation has been observed between cholesterol 25-hydroxylase, i.e., CH25H, mRNA expression and that of fibrosis markers in human intestinal samples from Crohn’s disease patients." (PMID 32182973, 2020).
diabetic kidney disease (1 paper, 2024). Progressive kidney disorder caused by vascular damage to the glomerular capillaries, in patients with diabetes mellitus. "This study shows that cholesterol 25‐hydroxylase (CH25H), a key enzyme in cholesterol metabolism, is expressed in kidney endothelial cells and protects against diabetic kidney disease." (PMID 38816950, 2024). "Our study demonstrates that CH25H, an endothelial cell‐specific gene that was upregulated in both mouse and human diabetic kidneys, is protective against diabetic kidney diseases, which could be a compensatory mechanism to prevent DKD progression." (PMID 38816950, 2024).
emphysema (1 paper, 2018). "Mice deficient in CH25H or the oxysterol receptor EBI2 exhibited decreased iBALT and subsequent CS‐induced emphysema." (PMID 29674392, 2018). "Similar to Ch25h−/− mice, these Ebi2−/− animals also failed to generate iBALT or any features of emphysema." (PMID 29674392, 2018). "Wild‐type mice developed clear evidence of emphysema accompanied by iBALT formation from 4 months onwards, that specifically associated with the airways further with vessels and septal tissue, whereas in Ch25h−/− mice formation of iBALT and the hallmarks of emphysema failed to develop." (PMID 29674392, 2018).
endometriosis (1 paper, 2024). The growth of functional endometrial tissue in anatomic sites outside the uterine body. "In the high JUP group, we identified several downregulated genes in the PBMCs from endometriosis patients, including HBB, HBA1, HBA2, RGPD2, CH25H, LTB, IFIT2 and JUN." (PMID 39684780, 2024).